KBTBD7 (kelch repeat and BTB domain containing 7)
Description:
As part of the CUL3(KBTBD6/7) E3 ubiquitin ligase complex functions as a substrate adapter for the RAC1 guanine exchange factor (GEF) TIAM1, mediating its 'Lys-48' ubiquitination and proteasomal degradation. By controlling this ubiquitination, regulates RAC1 signal transduction and downstream biological processes including the organization of the cytoskeleton, cell migration and cell proliferation. Ubiquitination of TIAM1 requires the membrane-associated protein GABARAP which may restrict locally the activity of the complex.
Synonyms: DKFZP434E2318
Tractability: Small molecule: it belongs to a druggable protein family. PROTAC: ubiquitination databases record sites on it.
Gene: Protein-coding gene on chromosome 13 (41,189,834 to 41,194,569, reverse strand). Ensembl gene ENSG00000120696.
Subcellular location: Cytoplasm; Nucleus
Pathways (Reactome):
Immune System: Antigen processing: Ubiquitination & Proteasome degradation
Metabolism of proteins: Neddylation
Signal Transduction: Regulation of RAS by GAPs
Gene Ontology:
Molecular function: protein binding; ubiquitin-like ligase-substrate adaptor activity
Biological process: proteasome-mediated ubiquitin-dependent protein catabolic process; protein K48-linked ubiquitination; regulation of Rac protein signal transduction; protein ubiquitination
Cellular component: Cul3-RING ubiquitin ligase complex; cytoplasm; cytosol; nucleus
Genetic constraint (gnomAD): Loss-of-function variants: 25 observed, 52.88 expected, observed/expected ratio (o/e) 0.47, 90% interval 0.34 to 0.66. The upper end of that interval is the gene's LOEUF score, 0.66, which puts it in group 2 of 6, group 1 being the genes least tolerant of losing a copy. Missense variants: 653 observed, 907.07 expected, observed/expected ratio (o/e) 0.72, 90% interval 0.67 to 0.77. Synonymous variants: 305 observed, 338.31 expected, observed/expected ratio (o/e) 0.9, 90% interval 0.82 to 0.99.
Homologues: Orthologues: chimpanzee KBTBD7 (100% identical), macaque KBTBD7 (99% identical), rat Kbtbd7 (95% identical), mouse Kbtbd7 (94% identical), guinea pig KBTBD7 (89% identical), pig KBTBD7 (84% identical). Paralogues in human: KBTBD6 (88% identical), KLHL20 (23% identical), KLHL17 (22% identical), KLHL3 (22% identical), KLHL2 (22% identical), KLHL21 (22% identical), KBTBD8 (22% identical), KLHL24 (22% identical), KLHL6 (22% identical), KLHL9 (21% identical), IPP (21% identical), KLHL13 (21% identical), and 42 more.
Diseases named in the same sentence as KBTBD7 in open-access papers:
KBTBD7 is named in the same sentence as 17 diseases in open-access papers, as found by Europe PMC text mining. Sharing a sentence is not in itself a finding about the gene and the disease. The quoted sentences say what the papers report.
myocardial infarction (2 papers, 2018 to 2022). Gross necrosis of the myocardium, as a result of interruption of the blood supply to the area, as in coronary thrombosis. "In 2018, KBTBD7 was shown to promote inflammatory responses in macrophages, and microRNA‐21 can directly target KBTBD7 to prevent cardiac dysfunction and inflammation after myocardial infarction." (PMID 35499228, 2022).
breast carcinoma (1 paper, 2021). "We also provide in vivo evidence that KBTBD7 regulates convergent extension during zebrafish gastrulation and functions as a tumor suppressor in breast cancer by promoting Vangl degradation." (PMID 33990333, 2021). "Further analysis in various subtypes of breast cancer also revealed a significant down-regulation of KBTBD7 in luminal, HER2-positive, and triple-negative breast carcinomas." (PMID 33990333, 2021). "Collectively, these results revealed that KBTBD7 plays an important suppressive role in breast cancer growth and metastasis through targeting Vangl proteins." (PMID 33990333, 2021). "Analysis of KBTBD7 in publicly available breast cancer TCGA (The Cancer Genome Atlas) datasets showed that KBTBD7 was down-regulated in breast carcinomas compared to normal breast tissues." (PMID 33990333, 2021). "Here, we found that expression of KBTBD7 degraded Vangl and significantly suppressed mammary tumor metastasis in murine xenograft models, confirming its negative role in regulating Wnt/PCP signaling." (PMID 33990333, 2021).
developmental delay (1 paper, 2024). "Moreover, other risk genes for developmental delay, such as BRD3, KBTBD7, and GATA3, also peaked during this stage, whereas SOX2 displayed high expression in a later lineage." (PMID 39363111, 2024).
heart failure (1 paper, 2023). Inability of the heart to pump blood at an adequate rate to meet tissue metabolic requirements. "Hub genes including LRRK2, BMI1, KBTBD7, and FFAR2 were associated with the risk of heart failure." (PMID 38137330, 2023).
lung carcinoma (1 paper, 2022). "Therefore, in this study, we investigate the role of KBTBD7 in non‐small cell lung cancer (NSCLC)." (PMID 35499228, 2022). "However, studies on the role of KBTBD7 in solid tumors, especially lung cancer, are still lacking." (PMID 35499228, 2022).
lymph node metastasis (1 paper, 2022). "In this study, we found that KBTBD7 was highly expressed in NSCLC tissues and positively correlated with histological type, differentiation, the P‐TNM stage, lymph node metastasis, and tumor size." (PMID 35499228, 2022).
Myocardial fibrosis (1 paper, 2021). "MiR-21 can inhibit apoptosis and inflammation by targeting KBTBD7, regulate angiogenesis through STRN/NOS3, and promote myocardial fibrosis through the TGF-β/Smad7 signaling pathway." (PMID 35111829, 2021).
non-small cell lung carcinoma (1 paper, 2023). A group of at least three distinct histological types of lung cancer, including non-small cell squamous cell carcinoma, adenocarcinoma, and large cell carcinoma. "Downregulation of KBTBD7 was demonstrated to inhibit cell proliferation and invasion of non-small cell lung cancer cells in vitro and small interfering RNA-mediated knockdown of RAC2 demonstrated antiproliferative and proapoptotic effects in prostate cancer cells." (PMID 36671500, 2023).
uterine cancer (1 paper, 2021). Primary or metastatic malignant neoplasm involving the uterine corpus and/or the cervix. "cBioPortal data analysis showed that KBTBD7 is deleted or mutated in a considerable number of prostate, bladder, and uterine cancer patients, further implicating its tumorigenic relevance in other cancer types and suggesting a potential tumor-suppressing function." (PMID 33990333, 2021).
cancer (4 papers, 2019 to 2022). A tumor composed of atypical neoplastic, often pleomorphic cells that invade other tissues. "However, the roles of KBTBD7 and SEC24B-AS1 in cancer have not been investigated." (PMID 31417870, 2019).
tumor (2 papers, 2021 to 2022). "Notably, KBTBD7 appears to have both tumor-promoting and tumor-suppressing functions." (PMID 33990333, 2021). "Statistical analysis revealed that KBTBD7 overexpression was positively correlated with histological type (p = 0.028), p‐TNM stage (p = 0.019), lymph node metastasis (p = 0.034), and tumor size (p < 0.01)." (PMID 35499228, 2022). "Immunohistochemical staining of 104 paired NSCLC and peritumoral normal specimens indicated that KBTBD7 was highly expressed in NSCLC tissues and positively correlated with the histological type, P‐TNM stage, lymph node metastasis, and tumor size." (PMID 35499228, 2022).
cardiovascular diseases (1 paper, 2018). "However, the role of KBTBD7 in cardiovascular diseases remains unclear." (PMID 29991775, 2018).
KBTBD7 also shares sentences with these, for which no sentence is quoted: cardiac ischemia (1 paper); prostate carcinoma (1); retinoblastoma (1); triple-negative breast carcinoma (1); uterine fibroid (1).